ZNF7 (zinc finger protein 7)
Description:
May be involved in transcriptional regulation.
Synonyms: KOX4; HF.16; zf30
Tractability: PROTAC: UniProt records ubiquitination sites on it; ubiquitination databases record sites on it.
Gene: Protein-coding gene on chromosome 8 (144,826,894 to 144,847,509, forward strand). Ensembl gene ENSG00000147789.
Subcellular location: Nucleus
Subcellular location (Human Protein Atlas): Mitochondria
Gene Ontology:
Molecular function: DNA binding; DNA-binding transcription factor activity, RNA polymerase II-specific; RNA polymerase II cis-regulatory region sequence-specific DNA binding
Biological process: regulation of transcription by RNA polymerase II; regulation of DNA-templated transcription
Cellular component: nucleus
Genetic constraint (gnomAD): Loss-of-function variants: 10 observed, 12.08 expected, observed/expected ratio (o/e) 0.83, 90% interval 0.51 to 1.4. The upper end of that interval is the gene's LOEUF score, 1.4, which puts it in group 5 of 6, group 1 being the genes least tolerant of losing a copy. Missense variants: 850 observed, 880.25 expected, observed/expected ratio (o/e) 0.97, 90% interval 0.91 to 1.02. Synonymous variants: 334 observed, 310.86 expected, observed/expected ratio (o/e) 1.07, 90% interval 0.98 to 1.18.
Homologues: Orthologues: chimpanzee ZNF7 (99% identical), macaque ZNF7 (97% identical), dog ZNF7 (81% identical), pig ZNF7 (81% identical), rabbit ZNF7 (80% identical), guinea pig ZNF7 (74% identical), mouse Zfp7 (69% identical), rat Zfp7 (68% identical). Paralogues in human: ZNF658 (43% identical), ZNF726 (43% identical), ZNF724 (43% identical), ZNF484 (42% identical), ZNF33B (42% identical), ZNF595 (42% identical), ZNF708 (42% identical), ZNF568 (41% identical), ZNF254 (41% identical), ZNF41 (41% identical), ZNF728 (41% identical), ZNF182 (41% identical), and 164 more.
Diseases named in the same sentence as ZNF7 in open-access papers:
ZNF7 is named in the same sentence as 3 diseases in open-access papers, as found by Europe PMC text mining. Sharing a sentence is not in itself a finding about the gene and the disease. The quoted sentences say what the papers report.
Arthritis (3 papers, 2020 to 2024). Inflammation of a joint. "ZnF7-mutant mice develop arthritis, supporting a ZnF7-dependent role for A20 in regulating TNF/TNFR1 signalling." (PMID 38467621, 2024). "The highlight of these studies is that the ZnF4 and ZnF7 ubiquitin-binding domains in A20 have been proven to be critical to the function of preventing inflammation-dependent arthritis, and exploration of the specific role of these domains has gradually progressed." (PMID 32958016, 2020).
enthesitis (1 paper, 2025). Inflammation at the site of insertion of ligaments, tendons, and other fibrous structures into bone. "In contrast, ZnF7 mutations result in PsA-like phenotypes, including psoriatic skin lesions, enthesitis, dactylitis, nail destruction, and distal interphalangeal joint (DIP) deformities." (PMID 41583484, 2025). "These mice presented with spontaneous skin lesions, spontaneous nail lesions, DIP deformations, polyarticular arthritis, axial arthritis, enthesitis, bone erosion, new bone formation at their distal phalanxes, resembling PsA phenotypes observed in ZnF7-mutant mice." (PMID 41583484, 2025).
glioblastoma (1 paper, 2024). The most malignant astrocytic tumor (WHO grade IV). "Like CCDC88A, the third-ranked result, Zinc Finger Protein 7 (ZNF7), has been associated with glioblastoma." (PMID 38630692, 2024). "In glioblastoma, ZNF7 has been reported as a survival marker." (PMID 38630692, 2024).